MIR7154 (microRNA 7154)
Synonyms: hsa-mir-7154
Gene: MicroRNA gene on chromosome 11 (45,691,704 to 45,691,776, reverse strand). Ensembl gene ENSG00000276639.
Homologues: Orthologues: chimpanzee MIR7154 (100% identical).